FTO (FTO alpha-ketoglutarate dependent dioxygenase)
Diseases named in the same sentence as FTO in open-access papers (continued):
Sharing a sentence is not in itself a finding about the gene and the disease.
Obesity (continued). "Our results showed that CXCL12 rs501120, LEP rs7799039, and FTO rs9939609 polymorphisms were associated with T2D in subjects with obesity, but not in subjects without obesity." (PMID 30764545, 2019). "For the FTO SNP rs8050136, homozygotes for the risk allele (A/A) have 1.67 times greater risk of obesity than those who do not have the allele." (PMID 31477138, 2019). "Therefore, in future studies to evaluate the effect of the FTO gene on body composition, obesity, and appetite, it is important to evaluate the level of expression and the interaction with other genes." (PMID 31810473, 2019). "Lifestyle modification may exert its effects on obesity through changes in the expression level of the FTO and IRX3 genes." (PMID 31126299, 2019). "Variants near FTO, MC4R, and NRXN3, all loci known to have substantial impact on variation in BMI, mapped to a cluster of T2D-risk variants thereby assumed to be driven primarily by obesity." (PMID 31322649, 2019). "FTO affected not only obesity phenotypes, but also osteoporosis phenotypes, like BMD." (PMID 31998240, 2019). "Administration of GC and GNN reduce weight and improve lipid and glucose blood profiles in people with overweight or obesity, although the presence of polymorphisms PLIN4, FTO and ADRB3 might hinder in some degree these effects." (PMID 29361938, 2018). "The FTO SNPs are known to affect glucose metabolism and hence lead to obesity." (PMID 29752338, 2018). "The finding of obesity and diabetes-associated FTO and SORBS1 as top hub proteins in AD-related M1 module is consistent with increasing evidence indicating the presence of shared pathways in the pathogenesis of AD, obesity, and diabetes." (PMID 29490708, 2018). "A duplication of the FTO gene leads to mental retardation, obesity, and some other abnormalities." (PMID 29677190, 2018). "Although recent studies suggested that FTO has an effect on BMI, at least partly, through the change in the expression levels of other obesity-related genes such as IRX3, Moreover, a complete LD was found in the present study between three neighboring SNPs of the first intron region of the FTO gene." (PMID 29677190, 2018). "Several studies have reported the relationship between FTO and obesity." (PMID 29677190, 2018). "In conclusion, obesity-related parameters were not different in physically active individuals expressing different risk variants of FTO rs9939609, although homozygous risk allele carriers exhibited higher cognitive restraint." (PMID 29686893, 2018). "A sex-specific effect of FTO variants on susceptibility to obesity have been shown, a study -in 2016- indicated that the effect of FTO variants on T2DM susceptibility in Japanese men but not women is mediated through FTO effect on BMI." (PMID 30170548, 2018). "Among these genes, the FTO gene is reported as the most important gene factor related to obesity." (PMID 29677190, 2018). "The primary finding from the present study was that obesity-related parameters were not different in physically active individuals carrying different risk variants of FTO rs9939609 SNP." (PMID 29686893, 2018). "The fat mass- and obesity-associated gene (FTO) is significantlyassociated with obesity, but the associations of FTO withobesity-related traits are not fully described." (PMID 29870569, 2018). "At FTO rs9939609 SNP, individuals homozygous for the risk allele (AA) weigh 3 kg more and have a 1.7-fold higher risk of obesity than those who do not carry a risk allele (TT)." (PMID 29686893, 2018). "Our study has replicated known body composition loci including SEC16B, FTO and NEGR1 and resulted in the discovery of new signals that may associate with an increased risk for obesity-related traits." (PMID 30026463, 2018). "This resulted in 1758 variables selected using collective feature selection (note that intersection of methods only selects 2 genes which do not include well known SNPs linked to obesity such as variants in FTO and MYO16)." (PMID 29713383, 2018).
Obesity (continued). "It is also known that obesity is associated with a higher risk of certain cancers, although no relation with the FTO gene polymorphism is known." (PMID 29675043, 2018). "The effect of obesity and diabetes on hepatic FTO expression is controversial." (PMID 30388740, 2018). "An improved understanding of the differences in dietary and physical activity patterns in variants of FTO rs9939609 SNP within a physically active cohort may provide a greater insight into the behaviours that offset FTO-mediated obesity." (PMID 29686893, 2018). "Interestingly, the FTO genotype can affect the success of lifestyle interventions in the prevention and treatment of obesity." (PMID 29850450, 2018). "In European patients with type 1 or type 2 diabetes, a genetic risk score constructed from confirmed obesity related SNP loci was associated with diabetic nephropathy, although FTO variant alone did not have significant effect on any of renal phenotype." (PMID 30566433, 2018). "However, no studies have been conducted to determine the genetic association of FTO variants with T2DM and/ or obesity." (PMID 30170548, 2018). "The aim of the present study was to assess the independent contributions of LEPR (rs1137101), FTO (rs9939609), MC4R (rs2229616 and rs17782313), and PPARG-2 (rs1801282) polymorphisms for clinically overweight or obesity phenotypes and endocrine-metabolic traits in prepubertal children." (PMID 29679223, 2018). "However, FTO appears to have a greater effect on obesity compared to all other obesity loci and this has been confirmed through replication studies throughout the life span and across ethnicities." (PMID 28859657, 2017). "One of the most known genetic factors predisposing humans to nonmonogenic obesity is a polymorphism in the fat mass and obesity-associated (FTO) gene especially first intron rs9939609 (A/T variant)." (PMID 28607773, 2017). "Examination of the FTO–diet interaction on obesity-related traits in an Asian Indian population showed that dietary fiber modified the association of the FTO SNP rs11076023 and waist circumference (WC), indicating that this effect was more pronounced on central obesity than on general obesity." (PMID 29273742, 2017). "Since obesity is known to be a predisposing factor for the development of T2D, it is not surprising that variants in FTO have been also found in T2D GWAS." (PMID 28953253, 2017). "This study indicated that RAS could ameliorate obesity induced by HFD and that the molecular mechanism might be associated with the expression of the FTO gene." (PMID 29098158, 2017). "Thus this study made an indigenous genetic study of obesity available, thus paving the way for proper management of obesity because PA, TSS, and energy intake showed modulating/mediating effect on the interaction between FTO and obesity." (PMID 28607773, 2017). "Although the investigation of the molecular function of FTO (fat mass and obesity associated) has not led to conclusive results, the gene plays a role in controlling feeding behavior and energy expenditure." (PMID 29126384, 2017). "Persistently overactivated FTO expression by continued cow’s milk consumption may maintain a state of hyperphagia promoting obesity." (PMID 28933365, 2017). "The polymorphism of FTO gene rs17817449 and GNB3 gene rs5443 (C825T) may be a genetic determinant of obesity in Saudi population, whereas impact of MC4R Asn274Ser change could not be detected in our sample." (PMID 29937877, 2017). "In HC mice, however, FTO expression was lowest and obesity was highest." (PMID 29098158, 2017). "Persistent milk signaling is thus a critical FTO-related epigenetic mechanism inducing obesity." (PMID 28933365, 2017). "The interaction of FTO SNPs and consumption of unhealthy food groups (e.g. salty snacks, sweets, and fried foods), which were typically energy dense with limited dietary fiber and nutritional value, was analyzed in other studies in relation to obesity." (PMID 29273742, 2017).
Obesity (continued). "While FTO is the first risk gene for obesity identified via genome-wide association studies, its exact mechanism remains unknown until two recent studies reported that IRX3, as FTO's target, probably inhibited the browning of white fat." (PMID 28988979, 2017). "This study shows a relationship between FTO and obesity phenotype and environmental/lifestyle factors might be an important modulator/mediator in the association." (PMID 28607773, 2017). "Given that available experimental evidence has shown that FTO modulates leptin receptor localization within neurons to control food intake and adiposity, our finding provides an additional insight into the linkage between FTO, leptin and adiposity, and obesity-related characters." (PMID 29212175, 2017). "The polymorphism of FTO gene rs17817449 and GNB3 gene rs5443 (C825T) may be a genetic determinant of obesity in Saudi population whereas impact of MC4R Asn274Ser change could not be detected." (PMID 29937877, 2017). "Previous reports of FTO-diet interactions demonstrate that the FTO effect on obesity may be modulated by a healthy dietary pattern." (PMID 29273742, 2017). "Telomere length (TL) attrition may be influenced by obesity-related inflammation and oxidative stress, and FTO gene-involved pathways." (PMID 28859657, 2017). "In the case of our BMI and obesity studies, chromosomal region 1q25 was previously shown to be related to BMI, obesity, and body fat percentage, whereas FTO was previously identified as a genetic determinant of BMI, obesity, body fat percentage, adiposity, and circulating leptin level." (PMID 28445147, 2017). "This highlights that FTO link with obesity could be mediated by epigenetic changes in DNA methylation." (PMID 28915859, 2017). "These FTO SNPs, which are in strong linkage disequilibrium (r2 > 0.80), are located in a cluster on the first intron of the gene on chromosome 16 and consequently exhibit similar obesity-related traits." (PMID 28103813, 2017). "However, only FTO–physical activity interactions in obesity have been adequately replicated in candidate gene studies." (PMID 28004149, 2017). "European adults who carried two copies of the risk allele in the FTO SNP, rs9939609, weighed about 3 kg more and had 1.67-fold increased odds of obesity in comparison with those with no copies of this allele." (PMID 29126384, 2017). "Evidence shows an interaction among the variants of obesity with environmental factors, as has been found for FTO, in which the lack of physical activity and less education potentiate the effect of its variants in the increase of obesity." (PMID 28690685, 2017). "The underlying loci of these two SNPs, FTO and MC4R, are well established obesity-related loci." (PMID 28448539, 2017). "An emerging hypothesis links obesity, shorter telomeres and accelerated aging, however, the manner in which the FTO gene fits into this hypothesis remains to be fully elucidated." (PMID 28859657, 2017). "A higher adherence to the Mediterranean dietary pattern (Med Diet) using Mediterranean diet scores (MDS) was associated with a decrease in obesity, regardless of FTO risk alleles." (PMID 28954439, 2017). "In accordance, FTO knockdown in mice decreased body weight, altered metabolism, and retarded growth, whereas FTO overexpression in mice led to a dose-dependent increase in body and fat mass, increased food intake resulting in obesity." (PMID 28933365, 2017). "The precise mechanism responsible for FTO’s effect on obesity in humans has been elusive." (PMID 28507607, 2017). "Importantly, we have discussed downstream genes and bi-directional feedback loops that influence obesity outcomes across FTO genotypes." (PMID 28859657, 2017). "In summary, we hypothesize that global energy sensors, AMPK, UCP2 and mTORC1, are likely to be influenced by FTO gene regulation, supporting the hypothesis that FTO functions in the process of obesity." (PMID 28859657, 2017).
Obesity (continued). "A recent report revealed that SNPs in FTO could influence obesity by altering the expression of the adjacent genes IRX3 and RPGRIP1L." (PMID 28208657, 2017). "Our findings on the FTO gene–fiber interaction therefore could have significant implications in public health for the prevention and management of obesity." (PMID 29273742, 2017). "Moreover, recent reports of obesity-related loci enriched in brain-expressed genes such as FTO, MC4R, GNPDA2, and BDNF point to a neuronal influence on body weight regulation in adults." (PMID 29212175, 2017). "While the homozygous mutation of FTO gene (FTO rs9939609 mutation) is associated to 3 kg heavier and had 1,7 fold increased risk of obesity than the homozygous non-risk allele carriers." (PMID 27894098, 2017). "The present study aimed to investigate FTO genotype–dependent metabolic changes in obesity and T2D." (PMID 27249024, 2016). "However, the specific mechanisms and signaling pathways by which FTO impacts adipogenesis and obesity remains incompletely characterized." (PMID 26907332, 2016). "Fewer studies in South Asians have been reported, two of which confirmed the association between the FTO locus and obesity susceptibility, whereas one study did not." (PMID 26878843, 2016). "We proposed that since obesity is a well established risk factor for CAD, it is likely that the FTO gene, as the BMI/obesity related locus, might confer the risk of CAD." (PMID 26878843, 2016). "In recent years, a small number of studies noticed the role of a group of common SNPs of FTO with regard to obesity, but there are still many unknowns regarding their function." (PMID 27196486, 2016). "Furthermore, the effect of FTO appears to be environment dependent among South Asians, resulting in a much stronger relationship with obesity and diabetes among urban relative to rural populations." (PMID 27458578, 2016). "Several studies have examined the influence of lifestyle factors such as diet and physical activity on the association between FTO variants and obesity traits; however, there are no studies to date among Asian Indians living in India." (PMID 27274759, 2016). "Also, we found that novel metabolites (PC aa C36:5, C38:5, C36:6 and C40:6) contribute to obesity and T2D based on FTO genotype." (PMID 27249024, 2016). "We hypothesized that the FTO protein and its partners that promote obesity may help in the survival of SUM149-MA TNBC cells under metabolic scarcity (prolonged lack of glutamine in medium) that kills 99.99% of SUM149 cells." (PMID 27390851, 2016). "The lack of an association between FTO genotype and placental FTO expression adds to emerging evidence of complex biology underlying the association between FTO genotype and obesity." (PMID 26907388, 2016). "This important role of FTO in kidneys implies a link between obesity and kidney." (PMID 26727661, 2016). "The correlation of FTO dysregulation with obesity, brain malformations and growth retardation was also reported, and suggested m6A may have important regulatory functions in these diseases." (PMID 27249342, 2016). "This raises the possibility that the effects of FTO genotype on fetal growth and postnatal obesity may have originated through IRX3 expression in embryonic life." (PMID 26907388, 2016). "Within this study, we aimed to assess whether the link between the FTO risk genotype and IRX3 and IRX5 expression in AT is related to the development of obesity and to alterations of AT biology in children." (PMID 27560134, 2016). "The obesity GWAS signals are localized to the first intron of FTO and apparently do not affect the amino acid structure of the protein but rather the expression of FTO." (PMID 26828654, 2016). "Flavonoids (particularly Luteolin) may act as an effective drug against FTO protein and could be therapeutically used for prevention of obesity." (PMID 27454254, 2016).
Obesity (continued). "In respect to the association of genotypes with obesity, under an additive model, the ORwas 1.25 (CI = 0.73 – 2.15) for PPARG rs1801282, 1.27 (CI = 0.82 –1.98) for FTO rs9939609, 1.47 (CI = 0.78 – 2.74) forADIPOQ rs4632532 and 1.43 (CI = 0.76 – 2.74) forADIPOQ rs182052." (PMID 27560839, 2016). "Loos RJ, Yeo GS: The bigger picture of FTO: the first GWAS-identified obesity gene." (PMID 27454254, 2016). "Our findings further extend previous work by identifying a specific gene, FTO, which has been associated with obesity but has not previously been explored with feeding practices." (PMID 27196523, 2016). "In addition, the association between dicamba use and prostate cancer was modified by genotype at rs4784336, located in an intronic region of the fat mass and obesity (FTO) gene." (PMID 27917368, 2016). "Future compounds designed to selectively inhibit FTO’s demethylase activity could be therapeutically useful for the treatment of obesity." (PMID 25830347, 2015). "Given the importance of the FTO locus, identifying potential POE may further improve our general understanding of the genetic mechanisms underlying obesity." (PMID 25793382, 2015). "Expression of FTO, the most widely replicated gene in genome-wide association study of obesity, was not affected by surgery (FDR = 0.99)." (PMID 25938420, 2015). "All these subjects were carrying at least 1 mutant (A) FTO allele but against their genetic predisposition, through intense physical exercise, they did not develop obesity while performing their professions." (PMID 25866584, 2015). "FTO is a relevant factor for the development of obesity and the metabolic syndrome in mice." (PMID 26691922, 2015). "This might be fundamental to understand the functionality of FTO in the etiology of obesity and related diseases." (PMID 25782772, 2015). "The exact molecular mechanism of how FTO might contribute to obesity is still under investigation, but high level of expression of FTO in the hypothalamus is suggestive of its role in food intake." (PMID 25825681, 2015). "Leanness may truly result from the manipulation of a gene important in energy balance (e.g., FTO inactivation leads to leanness, FTO overexpression leads to obesity)." (PMID 25825681, 2015). "Expression QTL studies in human brains revealed that obesity associated SNPs in FTO are associated with expression of IRX3, but not FTO itself." (PMID 25825681, 2015). "Consequently, we selected the FTO locus with the strongest polygenic obesity signal reported so far." (PMID 25793382, 2015). "Our findings provide novel mechanistic insight into how upregulation of FTO leads to obesity." (PMID 25881961, 2015). "The FTO gene was initially shown to influence human obesity and energy utilization." (PMID 25452335, 2015). "This could represent an exciting new mechanism by which FTO SNPs affect obesity and warrants further investigation." (PMID 26788058, 2015). "The genetic overlap between MDD and obesity/BMI is likely to extend beyond the FTO gene." (PMID 26125155, 2015). "Since then, many studies have confirmed the association between SNPs in intron 1 of FTO and BMI in non-European populations, notable East Asians, South Asians, Africans, Hispanics, and Native Americans, clearly demonstrating that the influence of FTO SNPs on obesity is a global trend." (PMID 26788058, 2015). "Therefore, our results suggest that there are ethnic differences with regard to the effects of FTO on obesity and body fatness." (PMID 24879436, 2014). "FTO has been well described in relation to body composition and obesity phenotypes." (PMID 24516669, 2014). "The relationship between the FTO gene and drug-induced obesity is unclear." (PMID 25278160, 2014). "However, the exact structure of the FTO protein as well as its physiological function and role in obesity development still need to be elucidated." (PMID 25102252, 2014).